MIR1237 (microRNA 1237)
Synonyms: hsa-mir-1237; MIRN1237
Gene: MicroRNA gene on chromosome 11 (64,368,602 to 64,368,703, forward strand). Ensembl gene ENSG00000221273.
Gene Ontology:
Biological process: miRNA-mediated post-transcriptional gene silencing
Cellular component: RISC complex